STAT6 (signal transducer and activator of transcription 6)
Diseases named in the same sentence as STAT6 in open-access papers (continued):
Sharing a sentence is not in itself a finding about the gene and the disease.
Obesity (18 papers, 2014 to 2024). Accumulation of substantial excess body fat. "Additionally, we showed in a previous study that GDF15, another mitokine, can be induced by Th2 cytokines/STAT6 signaling, thereby preventing metabolic impairment caused by obesity and insulin resistance." (PMID 34073755, 2021). "Mice with deficiency of Jak3 and Stat6 can display obesity and liver steatosis." (PMID 34506234, 2021). "Importantly, a significant reduction in the in situ proliferation of ATMs was observed in the HFD-treated STAT6-deficient mice as compared with that of wild-type mice, demonstrating an important role of IL-4 in driving the local proliferation of ATMs in obesity." (PMID 27031964, 2016). "Taken together, our results demonstrate that GCs have an important homeostatic function in regulating insulin sensitivity during obesity which is mediated through the cooperative activation of anti-inflammatory genes by GR and STAT6 in macrophages." (PMID 37080971, 2023). "In contrast, regions accessible in monocytes from subjects with obesity harbored binding sites for regulatory factors such as STAT6 and SMAD2." (PMID 34195568, 2021). "Recently, CD11b showed unexpected role in obesity-induced insulin resistance by limiting the proliferation and alternative activation of adipose tissue macrophages (ATMs) by inhibiting the IL-4/STAT6 signaling pathway." (PMID 30356719, 2018). "Consistent with this hypothesis, FoxO1 and Stat6 are reciprocally regulated, culminating in increased FoxO1 activity and decreased Stat6 activity in activated macrophages in obesity and type 2 diabetes." (PMID 35700043, 2022). "Similarly, miR-126 had altered expression in obesity and may modulate CCL2 (chemokine ligand 2) through genes that encode ETS1, MAX, NFKB1, RELB, and STAT6 proteins." (PMID 36355127, 2022). "Notably, AAMφ development is dependent on IL-4/IL-13 stimulation, which activates the transcription factor STAT-6, and STAT-6-deficient mice are more prone to obesity, oxidative stress in their AT and susceptibility to T2D development, which, in turn, is associated with the absence of AAMφs." (PMID 30443223, 2018). "Thus the IL-4/STAT6 signaling is the driving force for ATM proliferation in obesity." (PMID 27031964, 2016). "STAT6 also induces the expression of the transcription factor PPAR-γ, which cooperates with STAT6 to regulate macrophage polarization and increase the expression of AAM-type biomarkers in a murine model of obesity." (PMID 36439090, 2022). "Independent of leptin-deficient obesity and dietary obesity, a course of 8-week IL-4 supplementation improved obesity and impairment in Akt, STAT3, and STAT6 signaling." (PMID 32585823, 2020). "A course of 8-week IL-4 supplementation improves common phenotypes of obesity and impaired signaling pathways of Akt, STAT3, and STAT6 in the hypothalamic, hepatic, and epididymal fat tissues." (PMID 32585823, 2020). "The lack of STAT6 makes mice resistant to diet-induced obesity, and their adipocytes do not develop hypertrophy under high-fat-diet feeding." (PMID 39120327, 2024).
pulmonary fibrosis (18 papers, 2011 to 2026). Chronic progressive interstitial lung disorder characterized by the replacement of the lung tissue by connective tissue, leading to progressive dyspnea, respiratory failure, or right heart failure. "Shp2 is a cytoplasmic protein tyrosine phosphatase, and studies have shown that Shp2 deficiency enhances JAK1/STAT6 signaling induced by IL-4, promoting M2 polarization and increasing sensitivity to pulmonary fibrosis induced by bleomycin." (PMID 39910395, 2025). "Previous studies showed that bleomycin–induced lung fibrosis was diminished in mice deficient in IL-13, IL-4 and their downstream transcription factor STAT6 or treated with a neutralizing anti–IL-13 antibody." (PMID 29782549, 2018). "In addition, inhibition of STAT6 signaling by STAT6 inhibitor AS1517499 significantly enhanced the development of lung fibrosis, associated with reduced macrophage efferocytosis and elevated expression of pro-inflammatory cytokines." (PMID 35606692, 2022). "NAMPT promoted lung fibrosis by driving macrophage M2 polarization in an enzymatic-independent, STAT6-dependent manner." (PMID 38773984, 2024). "For example, the process of pulmonary fibrosis was promoted by inducing M2-typed polarization via the activation of the STAT-6/KLF-4/PPAR-γ signaling pathway." (PMID 37894541, 2023). "In contrast, activation of STAT6 signaling attenuated lung fibrosis, with improved macrophage phagocytosis and lung inflammation resolution." (PMID 35606692, 2022). "In any event, these observations collectively suggest that S1pr2 deletion in BALF cells impedes STAT6 activation and thereby inhibits the expression of STAT6–targeted profibrotic genes including Fizz1, leading to the attenuation of lung fibrosis." (PMID 29782549, 2018). "In the current study we investigated the essentiality of IL-1 and STAT6 signaling-mediated lung inflammation in MWCNT-induced lung fibrosis." (PMID 28903780, 2017). "The results also showed that while IL1-R1 signaling is redundant for lung fibrosis, STAT6 mediated Th2 response is essential in the process of fibrosis induced by biopersistent MWCNTs." (PMID 28903780, 2017). "The images support the involvement of STAT6 signaling in the development of MWCNT-induced lung fibrosis." (PMID 28903780, 2017). "We exposed IL-1R1 deficient mice or STAT6 deficient mice to Mitsui XNRi-7 (Mitsui-7), a MWCNT variant known to induce lung fibrosis in experimental rodents." (PMID 28903780, 2017). "The nuclear transcription factors which are blocked by col(V) treatment and implicated in pulmonary fibrosis are NF-κB, Sp1 and CCAAT/enhancer-binding protein β (Cebpb), SNAIL and STAT6." (PMID 24204629, 2013). "Additional studies have indicated that induction of FIZZ1 or YM1 transcripts are STAT6 dependent in bleomycin-induced lung fibrosis and allergic peritonitis model systems respectively." (PMID 22014099, 2011). "Liu et. al reported that induction of FIZZ1 transcripts was STAT6 dependent in a bleomycin-induced lung fibrosis model." (PMID 22014099, 2011). "In summary, our study revealed that NAMPT prompts pulmonary fibrosis by driving macrophage M2 polarization in an enzymatic-independent, STAT6-dependent manner; furthermore, our study paves the way to develop novel anti-pulmonary fibrosis strategies based on deletion of NAMPT in macrophage." (PMID 38773984, 2024). "In the bleomycin-induced mouse pulmonary fibrosis model, IL-4 and IL-13 levels were significantly increased, but after blocking the IL-4/IL-13 signaling pathway, the activation of STAT6 was reduced and which could significantly ameliorate pulmonary fibrosis." (PMID 34594474, 2021). "Finally, we confirmed the co-expression of STAT6 and PPARγ in the pulmonary fibrosis tissues of BLM-treated and Calca+/− rats, as well as synchronization of the cytoplasmic and nuclear entry of PPARγ and STAT6, thus confirming that αCGRP deficiency promotes PPARγ nuclear translocation." (PMID 37231189, 2023).
pulmonary fibrosis (continued). "Thus, STAT6 has a protective role in lung fibrosis through facilitating macrophage phagocytosis." (PMID 35606692, 2022). "CH25H/25-HC promotes M2 macrophage polarization through the AMPK/STAT6 pathway, thereby aggravating COPD-related pulmonary fibrosis." (PMID 41383739, 2025). "In a pulmonary fibrosis mouse model, TREM2 activation promoted STAT6 signaling, driving M2 polarization." (PMID 39910395, 2025). "Here, we ultimately confirmed that in BLM-induced mouse pulmonary fibrosis, NAMPT at least partially promotes macrophage M2 polarization by activating STAT6, which was consist with the previous report that STAT6 mediated M2 programing." (PMID 38773984, 2024). "Our study revealed that the deletion of USP25 can inhibit the STAT6/PPAR-γ signaling pathway by enhancing the ubiquitination of STAT6, thereby affecting macrophage M2 polarization, ultimately alleviating BLM-induced pulmonary fibrosis and bile duct ligation-induced liver fibrosis." (PMID 39781451, 2025). "In vitro experiments confirmed that the mechanism of NAMPT engaged in pulmonary fibrosis is related to the released NAMPT by macrophages promoting M2 polarization in a non-enzyme-dependent manner by activating the STAT6 signal pathway." (PMID 38773984, 2024). "STAT6 has also been shown to be part of the Th2 response activated by MWCNT exposure, and this healing response is a key event in the MWCNT-induced adverse outcome pathway leading to lung fibrosis." (PMID 28903780, 2017).
gastric cancer (17 papers, 2020 to 2025). A primary or metastatic malignant neoplasm involving the stomach. "circATP8A1, a potential prognostic biomarker and therapeutic target for gastric cancer, induces macrophage M2 polarisation and gastric cancer progression through the circATP8A1/miR-1-3p/STAT6 axis." (PMID 40176113, 2025). "They revealed that STAT6 was activated following exosome treatment of macrophages, highlighting the significant involvement of STAT6 in gastric cancer." (PMID 40443670, 2025). "The findings validated that the exosomes produced from gastric cancer cells, specifically circATP8A1, facilitate M2 macrophages polarization by competitively binding to miR-1-3p, hence activating the STAT6." (PMID 40443670, 2025). "Exosome-derived circATP8A1 from gastric cancer induces M2 polarization via the circATP8A1/miR-1-3p/STAT6 pathway, thereby facilitating tumor progression." (PMID 40443670, 2025). "Exosomal circATP8A1 derived from gastric cancer cells can regulate the miR-1-3p/STAT6 axis to induce macrophage M2 polarization, ultimately promoting proliferation and migration in gastric cancer." (PMID 41179289, 2025). "Experimental studies have shown that exosomal circATP8A1 derived from gastric cancer cells induces M2 polarization of macrophages and tumor progression through the activation of the circATP8A1/miR-1-3p/STAT6 axis." (PMID 39703839, 2024). "Single-cell sequencing data, WB, and immunofluorescence further confirmed the critical role of STAT6 in gastric cancer progression and macrophage M2 polarization." (PMID 38459596, 2024). "Our research uniquely illustrated that exosomal circATP8A1 derived from gastric cancer activated the STAT6 pathway by competitively binding to miR-1-3p, consequently fostering M2 macrophage polarization and amplifying the progression of gastric cancer." (PMID 38459596, 2024). "Through both in vitro and in vivo experiments, we demonstrated that exosomal circATP8A1 induces M2 polarization in macrophages by acting as a sponge for miR-1-3p, thereby regulating the STAT6 pathway and ultimately promoting the progression of gastric cancer." (PMID 38459596, 2024). "The TCGA database showed elevated levels of STAT6 expression in gastric cancer tissues which was confirmed by our immunohistochemical results in gastric cancer samples." (PMID 38459596, 2024). "In summary, exosome-derived circATP8A1 from gastric cancer cells induce macrophages M2 polarization via the circATP8A1/miR-1-3p/STAT6 axis, and tumor progression." (PMID 38459596, 2024). "Gastric cancer cell exosome circATP8A1 induces macrophage M2 polarization by competitively binding to miR-1-3p to activate the STAT6 pathway, which in turn promotes gastric cancer progression." (PMID 38459596, 2024). "In this study, we found that the STAT6 pathway was activated after exosome treatment of macrophages, revealing the important role of STAT6 in gastric cancer and M2 macrophages through single-cell sequencing and western blot." (PMID 38459596, 2024). "Activation of NF-κB and STAT1 pathways induced macrophage M1 polarization, exerting inflammatory functions and cytotoxic effects, whereas activation of STAT3 and STAT6 pathways mediated macrophage M2 polarization, suppressing tumour immunity and promoting gastric cancer progression." (PMID 38459596, 2024). "Thus, we explored the anti-tumor effect of DOP on gastric cancer cells by converting M2 into M1 subtype macrophage polarization via STAT6/PPAR-r and JAGGED1/NOTCH1 signaling pathways, as a result, DOP reduces apoptosis and prevents migration in gastric cancer." (PMID 37894541, 2023). "Furthermore, inhibition studies have indicated that targeting STAT6 signaling can suppress tumor growth and metastasis in gastric cancer." (PMID 36061181, 2022).
gastric cancer (continued). "Subsequently, IHC and western blot were performed on adjacent normal and tumor tissues extracted from gastric cancer patients to find that Th2 cell markers such as STAT6, GATA3 and the M2 cell polarization marker CD163 were significantly increased in patients with high ITGA5 expression levels." (PMID 33711961, 2021). "Thus, we proceeded to explore the impact of STAT6 on macrophages and gastric cancer." (PMID 38459596, 2024). "Subsequently, we analyzed the localization of STAT6 and the macrophage M2 polarization marker CD206 by immunofluorescence and found co-localization of STAT6 and CD206 in gastric cancer tissue, suggesting the involvement of STAT6 in macrophage polarization." (PMID 38459596, 2024). "In gastric cancer, it was reported that FSTL1 knockdown promotes apoptosis via the STAT6 signaling pathway." (PMID 34425560, 2021). "The expression of TP53BP1 positively correlated with the expression of cGAS, STING, and IRF3, while the expression of FANCD2 positively correlated with the expression of IRF3 and STAT6, suggesting the major role of DDR in SASP activation in early gastric cancers." (PMID 36061145, 2022). "Detailed analyses regarding these factors in reference to the clinical outcomes of early gastric cancers revealed that cases with STAT6-positive expression showed a longer progression-free survival time than those with STAT6-negative expression." (PMID 36061145, 2022). "Inhibition of the STAT6/ANO1 pathway reduced proliferation, migration, and invasion by gastric cancer cells, suggesting that the STAT6/ANO1 pathway could represent a novel therapeutic target for gastric cancer." (PMID 40396170, 2025). "This study reveals a novel mechanism driving immune evasion in gastric cancer, proposes FAP+CAFs as a potential biomarker for predicting anti-PD-1 therapy resistance, and suggests that targeting the IL-31/STAT6 axis could offer new therapeutic strategies to enhance immunotherapy efficacy." (PMID 40843362, 2025).
liver fibrosis (17 papers, 2017 to 2025). "Moreover, in C57BL/6 mice infected with Schistosoma japonicum, liver fibrosis is associated with enhanced phosphorylation of STAT6, in accordance with the hepatic upregulation of IL-4 and IL-13 receptors." (PMID 41409600, 2025). "It has been shown that the IL-4/STAT6 and IL-13/STAT6 signaling pathways exacerbate the progression of metabolically induced liver fibrosis in mice on HFD." (PMID 41409600, 2025). "Accordingly, pharmacological inhibitors or specific antisense oligonucleotides inhibiting STAT6 have shown interesting properties in vitro as well as in animal models to limit liver fibrosis or HCC occurrence/progression." (PMID 41409600, 2025). "Oral administration of a bioactive chitooligosaccharide limits liver fibrosis in CCl4-exposed mice through mechanisms implicating the JAK1/STAT6 pathway in M2 macrophages/Kupffer cells." (PMID 41409600, 2025). "Studies pointed out that IL-4 and IL-13 is capable of protecting against ischemia/reperfusion and inhibits inflammation; subsequently, it prevents hepatic fibrosis in drug-induced liver injuries through STAT6 activation." (PMID 36671504, 2023). "Studies have shown that inhibition of the STAT6/PPARγ pathway in liver fibrosis can reduce M2 macrophage polarization and delay fibrosis progression." (PMID 37231189, 2023). "Corilagin reduces liver fibrosis induced by S. japonicum infection via reducing the expression of IL-13/STAT6 signal pathway-related molecules in alternative activated macrophages." (PMID 31886304, 2019). "In contrast, IL-4, which is closely related to the injury-repair process and the accumulation of extracellular matrix proteins, plays a critical role in accelerating liver fibrosis by inducing collagen production via an IL-4Rα-STAT6-depentent mechanism." (PMID 28067328, 2017). "Therefore, it is possible that Stat6 similarly regulates the phenotype and function of IL-34 + IL-4 Mf in the treatment of liver fibrosis at the transcription factor level." (PMID 39856797, 2025). "Altered expression of these miRNA in macrophages (in a similar direction as we observed) has been implicated in lung and liver fibrosis via reduced STAT6 signaling; mir-142-5p targets SOCS1 (a negative regulator of STAT6 phosphorylation), and mir-130a-3p targets the PPAR-g inhibitor." (PMID 37344825, 2023). "STAT6 has pro- and anti-inflammatory effects, and its role in hepatic fibrosis is controversial." (PMID 36671504, 2023). "In addition, both TGF-β1/SMAD and IL-13/STAT6 pathways have been identified as major pathways that promote liver fibrosis in schistosomiasis by activating HSCs." (PMID 32944173, 2020). "Moreover, the IL-4/STAT6 activation could regulate liver fibrosis and cardiac fibrosis progression through targeting macrophages." (PMID 35784347, 2022). "Notably, a previous study indicated that inhibition of PTEN may regulate the polarization of M2 macrophages via activation of PI3K/Akt/STAT6 signaling in the progression of liver fibrosis." (PMID 34439276, 2021). "In addition, interleukin (IL)-4, which is closely related to the injury-repair process and accumulation of extracellular matrix proteins, plays a critical role in accelerating liver fibrosis by inducing collagen production via an IL-4Rα-STAT6-dependent mechanism." (PMID 28067328, 2017). "Suppressing the pathological progression of liver fibrosis by inhibiting TGF-β1/SMAD and interleukin-13 (IL-13)/signal transducer and activator of transcription 6 (STAT6) pathwaysvia directly targeting semaphorin 4D." (PMID 39314046, 2024). "Several important signaling pathways, such as mTOR/HIF-1α, TGF-β1/Smads, and JAK2/STAT6, are involved in the effect of paeoniflorin on activated HSC and ECM inhibition during liver fibrosis." (PMID 32410996, 2020).
liver fibrosis (continued). "In contrast, Sja-miR-71a derived from theS. japonicum egg-released EVs was reported to suppress the pathological progression of hepatic fibrosis by inhibiting the TGF-β1/SMAD and IL-13/signal transducer and activator of transcription 6 (STAT6) pathwaysvia directly targeting semaphorin 4D." (PMID 39314046, 2024). "In particular, IL-13 could initiate activation and differentiation of HSCs by enhancing TGF-β signaling through IL-4Rα and signal transducer and activator of transcription 6 (STAT6) in HSCs, promoting liver fibrosis." (PMID 30405626, 2018).